GSK3B (glycogen synthase kinase 3 beta)
Diseases named in the same sentence as GSK3B in open-access papers (continued):
Sharing a sentence is not in itself a finding about the gene and the disease.
cancer (continued). "Regarding cancer migration, β-sitosterol mainly acts through the protein kinase B/glycogen synthase kinase 3 beta (AKT/GSK-3b) and epithelial–mesenchymal transition (EMT) signaling pathways." (PMID 39065711, 2024). "Within this metabolic context, GSK-3β emerges as a crucial enzyme in regulating glucose metabolism in cancer cells." (PMID 39156976, 2024). "Contrary to its pathological roles in diseases other than cancer, activated GSK3β counters pro-oncogenic pathways such as those mediated by Wnt/β-catenin, Hedgehog, and Notch signaling and transcription factors (e.g., snail) that induce EMT in normal cells." (PMID 38318525, 2024). "For example, inhibition of GSK3β in human cancer cells results in centrosome dysregulation and abnormal mitosis." (PMID 39386585, 2024). "Consistently, we previously demonstrated that copper chelation therapy inhibited GSK3B phosphorylation and in turn induced downregulation of PD-L1 and increased anti-cancer immune response." (PMID 38642129, 2024). "GSK3β, a serine/threonine kinase, is integral in cancer due to its influence on a variety of cellular functions and signaling pathways." (PMID 38474160, 2024). "Previous studies have demonstrated that GSK3B is a serine/threonine protein kinase and its inhibition can suppress cancer progression." (PMID 38814517, 2024). "Elevated GSK3β levels are observed in several cancers, including ovarian, colorectal, and pancreatic cancers." (PMID 39596452, 2024). "Taken together, these results implied that the DNMT1-induced GSK3β inactivation promotes cancer cell death through abnormal glycogen metabolism." (PMID 38755637, 2024). "Similar results were observed in another paper, which reported that phosphorylation at Y216 was essential for β-TrCP-mediated ubiquitination of GSK3β in cancer cells." (PMID 38395742, 2024). "In our study, NRXN1 knockdown was shown to induce GSK3β phosphorylation at Ser9, which aligns with the established role of GSK3β in cancer progression." (PMID 39518976, 2024). "The activation of GSK3β enhances NF-κB-driven transcription of inflammation and metastasis-related genes that are dysregulated in cancer." (PMID 39596452, 2024). "Although GSK-3β and Cyclin D1 are known to be involved in cell cycle regulation, their relationship in cancer cells remains controversial." (PMID 39241034, 2024). "GSK3β also interacts with other pathways, like Hedgehog and Notch, contributing to the development and progression of cancer." (PMID 38474160, 2024). "The cytokinetic protein actinin α1 is shown to promote tumorigenesis and epithelial-to-mesenchymal transition (EMT) in cancer via AKT/GSK3β/β catenin signalling pathways." (PMID 38249992, 2024). "MYH9 also interacts with GSK3β and reduces its protein expression through ubiquitin-mediated degradation, thereby dysregulating the β-catenin destruction complex and inhibiting cancer stemness and EMT." (PMID 39550407, 2024). "GSK‐3β promotes constitutive NF‐kB signaling, which is important in cancer cell survival and growth." (PMID 39632551, 2024). "A typical feature of cancer is excessive cell proliferation, which can result from aberrant regulation of GSK3β." (PMID 39507759, 2024). "Subsequent experiments have comfirmed that the suppression of GSK3B expression mediates the anti-cancer properties of β-Sitosterol against HCC cell growth and metastasis." (PMID 38814517, 2024). "The development of inhibitors to suppress GSK3β is a focus in the quest to curb tumor growth and encourage apoptosis in cancer cells." (PMID 38474160, 2024). "In a mutant Kirsten rat sarcoma viral oncogene homolog (KRAS)‐like‐dependent human cancer cell line such as in Mia PaCa‐2 cells, the inactivation of GSK3‐β induces apoptosis via the accumulation of β‐catenin." (PMID 39632551, 2024).
cancer (continued). "On the other hand, Wnt activation inhibits GSK3β by binding to the Axin-bound-GSK3β complex, promoting mTOR signaling and cancer cell proliferation." (PMID 39766864, 2024). "These novel insights suggest that targeting GSK-3β in cancer immunotherapies must consider its dual role in CD8 T cell responses." (PMID 39340067, 2024). "GSK3β serves as an important regulatory enzyme in maintaining cell metabolic balance, especially in processes such as glycogen synthesis and glycolysis in cancer cells." (PMID 38755637, 2024). "On the contrary, in certain cancers GSK-3β inhibitors reduced cell proliferation and enhanced cell death upon irradiation treatment." (PMID 38367137, 2024). "Exploiting GSK3β′s multifaceted role in these areas is increasingly seen as a promising strategy for enhancing the efficacy of cancer treatments, potentially leading to improved patient outcomes." (PMID 39156976, 2024). "Negative regulation of GSK3β is caused by the PI3K/AKT pathway, which is frequently overactive in cancer." (PMID 39507759, 2024). "EYA transcription coactivator and phosphatase 4 (EYA4) interacted with PI3K/AKT, Wnt/GSK-3β and various signal proteins of cell cycle pathway, and played its role in promoting or inhibiting cancer." (PMID 39170242, 2024). "Corresponding “signaling hub” functions of GSK-3β have been revealed in other models, where GSK-3β regulated cell proliferation, quiescence and invasiveness, coordinating microenvironmental adaptation of cancer cells with their metabolism." (PMID 39135106, 2024). "The pro-oncogenic activity of deregulated GSK-3β sustains cancer cell survival, proliferation, migration, and invasion by suppressing or enhancing a broad range of molecular pathways." (PMID 37108703, 2023). "GSK3β plays important roles in the pathogenesis of cancer, while GSK3α has long been considered a functionally redundant protein of GSK3β." (PMID 37031867, 2023). "As a result, the Akt/GSK-3β/β-catenin signaling pathway has been indicated as an important therapeutic target for drug design to inhibit progression in many types of cancer cells." (PMID 37047425, 2023). "NCYM stabilizes MYCN and β-catenin via direct binding and inhibition of GSK3β and promotes cancer progression in various tumors." (PMID 38074684, 2023). "Taken together, these findings indicate that GSK3β inhibitors are positive regulators of the immune response against cancers, as well as negative regulators of the immune response in autoimmune conditions." (PMID 36672256, 2023). "Some components of the Wnt pathway, such as GSK-3β, are involved in both cancer and neurodegeneration but serve different roles." (PMID 38002524, 2023). "Western blotting was used to investigate the expression levels of galectin-3 and GSK3B proteins in the normal cell line, (SVGp12), and in cancer cell lines (GBM8401, GBM8901, U87-MG, and G5T)." (PMID 37185758, 2023). "We explored the GSCA to determine the drug sensitivity profile data of c-Met/GSK3β/MYC/CCND1 against different cancer cell lines." (PMID 36672275, 2023). "In mammals, GSK3β regulates important life activities such as proinflammatory response, anti-inflammatory response, immunity, and cancer development." (PMID 36995259, 2023). "GSK3β can shuttle between the cytoplasm and the nucleus, and after entering the nucleus, GSK3β can block the transcription factors required for cancer proliferation." (PMID 37398678, 2023). "The expression of glycogen synthase kinase-3β (GSK-3β) plays an important role in regulating growth, cell cycle progression, apoptosis, and cancer cell invasion in HNSCC." (PMID 37760799, 2023). "Numerous studies have considered galectin-3 or Glycogen synthase kinase 3 beta (GSK3B) as a potential prognosis marker for various cancers." (PMID 37185758, 2023). "GSK3α and GSK3β are distinct isoforms, with GSK3β studied in cancer development while GSK3α was considered redundant." (PMID 37031867, 2023).
cancer (continued). "AKT and GSK3β are often phosphorylated in dysregulated cancer signaling that arises from aberrant RTK activity." (PMID 38213538, 2023). "EPHB2 acts through driving Src/Akt/GSK3β/β-Catenin signaling cascades and regulates cancer stemness and drug resistance." (PMID 38259452, 2023). "Lithium inhibition of GSK3β suppresses cadherin-11, which is involved in cell–cell adhesion, cancer cell invasion, and metastasis of cancer." (PMID 36836894, 2023). "The most common isoform is GSk3β which overexpressed in different human cancer, that why it considers as strong therapeutic target." (PMID 37759329, 2023). "In this study, a library of 4,222 anti-cancer compounds underwent rigorous computational screening to identify potential candidates for targeting the binding pocket of GSK3β." (PMID 37284581, 2023). "The inactivation of GSK-3β via phosphorylation has previously shown significant inhibition in cancer cell growth and migration in HNSCC." (PMID 37760799, 2023). "In this study, an insilico screening approach was employed to investigate potential anti-cancer compounds targeting the GSK3β protein." (PMID 37284581, 2023). "Components of the Wnt signal pathway, including GSK3β, play central roles in cancer development and homeostasis." (PMID 37373005, 2023). "This modification reduces the stability of β-catenin through ubiquitination induced by GSK3β, which leads to a decrease in cancer cell proliferation." (PMID 38036730, 2023). "Inhibition or modulation of GSK3β activity has shown promise as a strategy to treat various disorders, including cancer and neurodegenerative diseases." (PMID 38139062, 2023). "Inhibition of β-TrCP or certain specific molecules that inactivate GSK3β can in turn block PD-L1 ubiquitination, promote its stability, and ultimately induce cancer immunosuppression." (PMID 37554324, 2023). "GSK3β has been reported to promote nuclear localization of NFκB and regulate the expression of antiapoptotic factors in some cancers, including AML." (PMID 36819180, 2023). "There is increasing evidence that the aberrant activity and expression of GSK3β promote the progression of various cancer types and their resistance to pharmacological or radiological treatments." (PMID 37108703, 2023). "On the other hand, GSK3B expression has been described to inhibit the progression of several cancer models, such as, among others, lung, gastric, and hepatocellular cancers." (PMID 37208504, 2023). "The hinge-interacting, aminothiazole group is common in third-generation cephalosporins, justifying the observed supremacy of this class in counteracting the effects of GSK3β downstream substrates in cancer and AD." (PMID 37057264, 2023). "Several inhibitors of GSK3β have been developed and progressed to early-stage clinical trials for various types of cancer." (PMID 37284581, 2023). "GSK3β inhibitors are now being used to treat a variety of conditions, including Alzheimer’s disease, diabetes, and cancer." (PMID 37284581, 2023). "In this study, we provided evidence for the mechanism by which cephalosporin antibiotics exert their beneficial effects against cancer and AD, namely, by inhibiting GSK3β." (PMID 37057264, 2023). "Salvigenin exerted its cancer-suppressing function in the context of HCC by hampering the PI3K/AKT/GSK-3β signaling pathway." (PMID 37129745, 2023). "Previous studies have shown the potential of targeting the Akt/GSK-3β/β-catenin signaling pathway to inhibit cancer cells progression." (PMID 37047425, 2023). "SLFN5 downregulates membrane type 1 matrix metalloproteinase (MT1-MMP) expression through the AKT/GSK-3β/β-catenin pathway in several types of cancer cells, exerting inhibitory effects on migration and invasion." (PMID 37771431, 2023). "Multiple oncogenic signaling cascades (EGFR, CXCR4, FASN, P-gp, β-catenin, GSK-3B, STAT1, JAK2, MUC1, etc) are hallmarks of cancer cells that are associated with drug resistance, tumorigenic potential, and metastasis." (PMID 37151801, 2023).
cancer (continued). "The negative regulation of canonical Wnt signaling in cancer depends on the GSK3β-induced phosphorylation and the E3 ubiquitin ligase-induced ubiquitination of β-Catenin." (PMID 36123332, 2022). "Active GSK-3β is considered a cancer suppressor as it promotes the destruction of several oncogenic proteins [e.g., β-catenin, c-Myc, and myeloid cell leukemia sequence 1 (MCL-1)]." (PMID 35847921, 2022). "Data published in the last 15 years have demonstrated the oncogenic role of GSK-3β, making it a very promising target for treating cancer." (PMID 36430630, 2022). "Studies from our group and others have demonstrated that CD151 regulates the ERK and GSK-3β signaling pathways in multiple types of malignant tumors." (PMID 36209197, 2022). "GSK-3β plays an important role in cancer types that are resistant to chemotherapy, radiotherapy and targeted therapy." (PMID 34719320, 2022). "GSK3β, a serine/threonine protein kinase, is a key enzyme involved in various diseases, including cancer." (PMID 35350242, 2022). "By interfering with the PP2A-mediated dephosphorylation, SET activates oncogenic signaling such as AKT, ERK, c-MYC and GSK3-β to promote the survival and proliferation of cancer cells." (PMID 36345878, 2022). "This process can be reversed by Akt-induced phosphorylation of GSK-3β, resulting in the accumulation of β-catenin, thus inducing the growth and metastasis of cancer cells." (PMID 36345477, 2022). "The role of GSK-3β in the Wnt pathway, initially, caused GSK-3β to appear as if it has played an anti-cancer role for many years." (PMID 36430630, 2022). "Many studies showed pro- and anti-oncogenic roles of GSK-3β in many cancers including in pancreatic ductal adenocarcinoma (PDAC)." (PMID 36430630, 2022). "In summary, metastasis of cancer cells in bone activates GSK‐3β/Drp1 pathway, resulting in mitochondrial fission and dysfunction, activating NLRP3 inflammasome and consequently inducing nociceptive response." (PMID 35689386, 2022). "These combinations offer achieving higher radio- and chemo- sensitization through alteration in the key signaling pathways such as AMPK, STAT3, NF-ĸB, Hedgehog, PI3K/Akt/mTOR, Notch, GSK3β, and Wnt related to cancer stemness and drug resistance." (PMID 35740529, 2022). "Therapeutic inhibition of GSK-3β has been shown to reduce cancer cell proliferation and survival in different malignant neoplasms, with combination treatments suggesting a viable method to avoid treatment resistance." (PMID 36430630, 2022). "In DU145 cells, TUBB4A KO or MYH9 KD increased the expression of GSK3β but decreased the expression of nuclear β-catenin and its downstream targets, cyclin D1 and c-MYC, suggesting TUBB4A/MYH9-mediated GSK3β/β-catenin signaling in human cancer cells." (PMID 35589707, 2022). "This Gα13-AKT-mediated inhibition of GSK3β activity led to increased β-catenin translocation to the nucleus and induced a transcriptional program that promoted cancer cell invasion and metastasis." (PMID 34689178, 2022). "The inhibition of GSK-3β significantly reduced the proliferation and survival of cancer cells, sensitized them to gemcitabine and ionizing radiation, and attenuated their migration and invasion." (PMID 36430630, 2022). "Glycogen synthase kinase 3 beta (GSK3β), a highly evolutionarily conserved Ser/Thr kinase, is engaged in the cancer development and progression through its selective phosphorylation of substrate proteins." (PMID 35090098, 2022). "Many experiments have shown that TPs can regulate a variety of signaling pathways in cancer cells, including the GSK-3β phosphorylation." (PMID 35836256, 2022). "The results showed that ABHD2, DCAF7, and GSK3B were upregulated in cancer tissues compared with normal prostate tissues with high or medium intensity." (PMID 36468011, 2022). "We showed that GSK3B is significantly more activated in drug-resistant vs. responsive CRC patients and is associated with cancer progression, poor response to therapy, and worse OS." (PMID 35582524, 2022).
cancer (continued). "The detailed pathways regulated by GSK-3β in cancer in general were discussed in detail in many published reviews." (PMID 36430630, 2022). "For example, GSK3α was found to play a more important role than GSK3β in survival of cancer cells, during resistance to bortezomib-induced cancer treatment." (PMID 35292059, 2022). "Retrospective studies showed lower cancer incidence in psychiatric patients treated with Li therapy for bipolar disorder than in a control group not receiving Li therapy, which was suggested to be due to Li controlling cancer cell growth via inhibiting GSK-3β." (PMID 36278631, 2022). "The phenotype of PS female primitive cells with active GSK3β and Wnt5a-dependent proliferative capacities is reminiscent of cancer stem cells." (PMID 36283083, 2022). "A chimeric anti-ENO1 monoclonal antibody (ChenO1-22) can attenuate cancer cell invasion by inhibiting ENO1-mediated GSK3β inactivation to promote SLUG protein ubiquitination and block metastasis." (PMID 36620599, 2022). "There are multiple ongoing clinical trials testing GSK-3β inhibitors in cancer patients including four studies in PDAC patients." (PMID 36430630, 2022). "In consistence with these observations, our results showed that enhanced METTL14 in cancer cell lines indeed activated Wnt/β‐catenin signalling pathway and elevated phosphorylated GSK3β." (PMID 36264762, 2022). "GSK3β is involved in glycogen synthesis and multiple signalling pathways linking the protein to disorders ranging from neurodegenerative diseases to cancers, and involving differentiation, proliferation, motility, and apoptosis." (PMID 36430630, 2022). "Pharmacological and molecular inhibitions of GSK-3β in K-ras-mutant PDAC cancer models showed upregulation of c-Myc and β-catenin leading to apoptosis induction, and indicative treatment selection of only malignant pancreatic epithelial cells." (PMID 36430630, 2022). "It is now clear that GSK3-β is a powerful pro-cancer protein and is a perfect candidate for treating PDAC and many other cancers." (PMID 36430630, 2022). "In summary, this study demonstrates that eEF2K enhances PD-L1 stability and expression via GSK3β inactivation, leading to cancer cells escape from immune surveillance." (PMID 35347072, 2022). "Strictly speaking, Akt (Protein kinase B)/GSK-3β (Glycogen synthase kinase-3β)/β-catenin signaling pathway is recently discovered for the etiology of cancer diseases." (PMID 36432024, 2022). "On the other hand, the pro-oncogenic effects of GSK-3β are supported by strong data and interact with critical up-regulated proteins in the cancer progression such as K-ras and NF-κB." (PMID 36430630, 2022). "Emerging date has also indicated that GSK-3β mediated the activation of the NF-κB signalling cascade via enhancing the NF-κB transcriptional activity in the nucleus to promote cancer." (PMID 35355860, 2022). "Most of these studies were published between 2001 and 2010 when the pro-cancer role of GSK-3β was not well known." (PMID 36430630, 2022). "Based on the previous data, multiple laboratories have been working on developing GSK-3β inhibitors for treating cancer." (PMID 36430630, 2022). "GSK-3β phosphorylates β-catenin, triggering its degradation, and consequently reducing β-catenin nuclear accumulation and reversing the pro-cancer Wnt/βcatenin pathway." (PMID 36430630, 2022). "Studies have shown that the Akt/GSK‐3β signalling pathway plays an important role in the occurrence of various cancers." (PMID 35567291, 2022). "In this mini-review, we discuss the suggested anti-cancer roles of GSK-3β and question their relevance to PDAC." (PMID 36430630, 2022). "Many studies have shown that UBE2T affects AKT/GSK3‐β, as well as Wnt/β‐catenin pathway in many types of cancer including HCC." (PMID 34614271, 2022). "Multiple studies showed pro- and anti-cancer roles of GSK-3β creating confusion about the benefit of targeting GSK-3β for treating cancer." (PMID 36430630, 2022).